SLC18B1 (solute carrier family 18 member B1)
Description:
Proton-coupled polyamine antiporter involved in the translocation of polyamines from cytosol into secretory vesicles prior to their release via exocytosis. Uses the electrochemical proton gradient generated by a V-type proton-pumping ATPase to couple the efflux of protons with the uptake of a polyamine molecule. Facilitates vesicular storage of spermine and spermidine in astrocytes with an impact on glutamatergic neuronal transmission and memory formation (By similarity). Upon antigen stimulation, regulates polyamine accumulation and release in mast cell secretory granules, which in turn potentiates mast cell degranulation and histamine secretion (By similarity).
Synonyms: VPAT; C6orf192; dJ55C23.6
Tractability: Antibody: UniProt predicts a signal peptide or a membrane-spanning region. PROTAC: ubiquitination databases record sites on it.
Gene: Protein-coding gene on chromosome 6 (132,769,370 to 132,813,339, reverse strand). Ensembl gene ENSG00000146409.
Subcellular location: Cytoplasmic vesicle, secretory vesicle membrane; Cytoplasmic vesicle, secretory vesicle, synaptic vesicle membrane
Subcellular location (Human Protein Atlas): Golgi apparatus; Cytosol
Gene Ontology:
Molecular function: monoamine:proton antiporter activity; polyamine:proton antiporter activity; transmembrane transporter activity
Biological process: serotonin uptake; spermidine transport; spermine transport; polyamine transmembrane transport; proton transmembrane transport; transmembrane transport
Cellular component: secretory granule membrane; synaptic vesicle membrane; transport vesicle membrane
Genetic constraint (gnomAD): Loss-of-function variants: 44 observed, 36.79 expected, observed/expected ratio (o/e) 1.2, 90% interval 0.94 to 1.54. The upper end of that interval is the gene's LOEUF score, 1.54, which puts it in group 6 of 6, group 1 being the genes least tolerant of losing a copy. Missense variants: 503 observed, 462.67 expected, observed/expected ratio (o/e) 1.09, 90% interval 1.01 to 1.17. Synonymous variants: 192 observed, 176.36 expected, observed/expected ratio (o/e) 1.09, 90% interval 0.97 to 1.23.
Homologues: Orthologues: chimpanzee SLC18B1 (99% identical), macaque SLC18B1 (90% identical), rabbit SLC18B1 (85% identical), dog SLC18B1 (85% identical), pig SLC18B1 (85% identical), mouse Slc18b1 (80% identical), rat Slc18b1 (79% identical), guinea pig SLC18B1 (68% identical), tropical clawed frog slc18b1 (59% identical), zebrafish slc18b1 (51% identical), Caenorhabditis elegans vpat-1 (36% identical). Paralogues in human: SLC18A1 (24% identical), SLC18A2 (23% identical), SLC18A3 (19% identical).
Diseases named in the same sentence as SLC18B1 in open-access papers:
SLC18B1 is named in the same sentence as 4 diseases in open-access papers, as found by Europe PMC text mining. Sharing a sentence is not in itself a finding about the gene and the disease. The quoted sentences say what the papers report.
atherosclerosis (1 paper, 2019). A disease characterized by the build-up of fatty material and calcium deposition in the arterial wall resulting in partial or complete occlusion of the arterial lumen. "Here the authors develop a small molecule fluorescent probe specific to activated M1 and M2 macrophages, identify the orphan receptor Slc18b1/SLC18B1 as the mechanism of uptake, and use it to image atherosclerosis in mice." (PMID 30846702, 2019).
glioma (1 paper, 2025). A benign or malignant brain and spinal cord tumor that arises from glial cells (astrocytes, oligodendrocytes, ependymal cells). "SLC47A1, GPC1, CAV1, and SLC18B1 are involved in polyamine transport; however, only CAV1 has been extensively studied in gliomas and is involved in stemness and temozolomide resistance." (PMID 40761256, 2025).
cancer (2 papers, 2020 to 2022). A tumor composed of atypical neoplastic, often pleomorphic cells that invade other tissues. "SLC18B1 (MFS-type transporter SLC18B1) has not yet been functionally linked to cancer, but we suggest it could be a viable target for OS treatment." (PMID 32581649, 2020).
SLC18B1 also shares sentences with these, for which no sentence is quoted: asthma (1 paper).